CD24 (CD24 molecule)
Diseases named in the same sentence as CD24 in open-access papers (continued):
Sharing a sentence is not in itself a finding about the gene and the disease.
breast cancer (continued). "Then, we tuned the aggregated parameters using the biological constrains, described in Material and Methods, combined with the experimental values of breast cancer volumes and the proportion of CSCs derived from the percentage of Sca-1+ and CD44+/CD24− cells." (PMID 25184361, 2014). "On the breast cancer SUM159 cell line, CCAST reveals at least 5 distinct cell states based on two surface markers (CD24 and EPCAM)." (PMID 25078380, 2014). "The first identification of CSCs in solid tumors was made in 2003, when CSCs were identified and isolated from breast cancers using CD44 and CD24 markers." (PMID 24528676, 2014). "The cell surface markers CD44 and CD24 are adhesion molecules and CD44+CD24− cells were suggested to be breast cancer stem cells." (PMID 24363201, 2014). "Breast cancer cell lines (MDA-MB-231, MDA-MB-468, MCF7 and T47D) and primary human breast cancer cells were labelled with pre-conjugated with fluorescently antibodies to CD44, CD24 and ESA (stem cell markers), 7-AAD (viability marker) and Hoechst (Cell cycle)." (PMID 25277201, 2014). "Nevertheless, in certain breast cancer patients, CD44+/CD24- cells are still sensitive to radiotherapy, suggesting that not all breast CSCs are radioresistant and that not all CD44+/CD24- cells are CSCs." (PMID 23799994, 2013). "In vitro findings suggest that breast cancer cells with lymphatic metastatic ability and expressing the CD44+/CD24- immunophenotype have clonogenic potential and a higher ability to survive and grow in unfavorable environments." (PMID 23419168, 2013). "Clones of non-invasive CD44+CD24+ sorted cells from Ca1a, ZR75.1 and MCF7 breast cancer lines transplanted into immunocompromised mice gave rise to molecularly heterogeneous tumors that exhibited local invasion." (PMID 23986719, 2013). "We quantified the frequency of asymmetric segregation of template DNA strands in 12 human breast cancer cell lines, and correlated the frequency to molecular subtype, CD44+/CD24-/lo phenotype, and invasion/migration ability." (PMID 24238140, 2013). "In concordance to our findings in breast cancer cell lines, primary cancer tissues of triple negative breast cancer had higher frequency of ALDH+ and CD44+CD24- cells." (PMID 23883436, 2013). "To test these scenarios, we co-cultured 3 breast cancer cell lines with human MSCs and analyzed expression of CD44 and CD24." (PMID 24238140, 2013). "In breast cancer, CSCs have been identified as CD44+CD24-/low or aldehyde dehydrogenase positive (ALDH+)." (PMID 23883436, 2013). "When we co-cultured breast cancer cells with MSCs, we observed a marked expansion of the CD44+/CD24-/lo CSC population, and a switch from asymmetric to symmetric segregation of template DNA." (PMID 24238140, 2013). "Breast cancer cells with CD44+CD24− were identified as CSCs, which form heterogeneous tumors with CD44+/− and CD24+/− phylogeny." (PMID 23626764, 2013). "Several stemness markers have been described for the various histological subtypes of breast cancer, among them CD44, CD24, CD133, EpCAM, CD166, Lgr5, CD47, ALDH1 and the most recent ABCG2." (PMID 23976904, 2013). "CD44+CD24− cells have been proposed to represent cancer stem cells in breast cancer, as well as in head and neck squamous cell carcinoma (the latter includes an ALDH1+CD44+CD24− stem cell subset)." (PMID 23484127, 2013). "Further, the impact of ATG4A expression on sphere formation of breast cancer cell lines from different sub-types, namely basal MDA-MB-231 (CD44+/CD24-) and luminal MCF-7 cells (CD44-/CD24+) was analysed." (PMID 24229464, 2013). "CD24 is the most widely used marker, together with CD44, for identifying tumor-initiating cells in breast carcinomas." (PMID 23671674, 2013). "Leukemia stem cells have been isolated from acute leukemic cells, and the first CSC/CIC population was isolated from breast carcinoma with the combination of CD44 and CD24 expression." (PMID 23967051, 2013).
breast cancer (continued). "Representative data from our S2N and S2 cell lines also challenge the validity of the CD24−/CD44+ marker combination and EpCAM expression as tumorigenicity markers in breast cancer." (PMID 23042145, 2012). "The ability of the conserved regions to direct gene expression was tested using three previously characterized human breast cancer cells, MDA-MB-231, SUM159, and MCF7, each with a different CD44/CD24 expression profile." (PMID 23226410, 2012). "Compared to MCF-7, both the upregulation of CD44+CD24–/low subpopulation ratio and IC50 of adriamycin indicated that breast cancer stem cells displaying chemoresistance would also play an important role in tamoxifen resistance." (PMID 23554768, 2012). "Cells with stem cell characteristics have been prospectively isolated from breast cancer using CD44 and CD24 as markers, which are present on Hs578T and MDA-MB-231 cells." (PMID 22235336, 2012). "In breast cancer cells, Twist expression correlates with an increase of TIC parameters such as CD24−/CD44+ expression, enhanced ALDH1 activity and a higher SP fraction." (PMID 23042145, 2012). "Breast cancer samples displayed four distinct cell sub-populations based on their membrane expression pattern (CD44+/CD24−, CD44+/CD24+, CD44−/CD24+ and CD44−/CD24−), and merged images showed excellent CD44/CD24 co-localisation, when present." (PMID 23028444, 2012). "In several in vitro breast cancer models, the CD24+/CD44+ population declined but the CD24−/CD44+ fraction increased after herceptin treatment." (PMID 23042145, 2012). "In breast cancer, CD44+CD24−/low, aldehyde dehydrogenase (ALDH1), and CD133 have been considered as markers of CSCs." (PMID 23049880, 2012). "Using these methods, we showed that the breast carcinoma cells displayed four distinct sub-populations based on the expression pattern of CD44 and CD24." (PMID 23028444, 2012). "Using this method, the breast carcinoma cells displayed four distinct staining patterns on the basis of cell membrane positivity (CD44+/CD24−, CD44+/CD24+, CD44−/CD24+ and CD44−/CD24−)." (PMID 23028444, 2012). "The differences in CD44+/CD24− tumour cell proportions and ALDH1 positivity between the subtypes of breast cancer were statistically significant." (PMID 21559013, 2011). "Human breast cancer stem cells were initially isolated by high expression of CD44 and low expression of CD24." (PMID 24212780, 2011). "In breast cancer, prospective TICs have been isolated by flow cytometry by using cell surface antigens, such as CD44 and CD24." (PMID 21952072, 2011). "Flow cytometry—Analysis of breast cancer stem cell markers including CD44, CD24, CD49f and aldehyde dehydrogenase 1 (ALDH1)." (PMID 24212798, 2011). "To confirm this, we initially isolated BCSCs from malignant breast tumors based on their CD44 and CD24 expression pattern." (PMID 22152097, 2011). "The present study showed that putative CSCs identified by CD44/CD24 and ALDH1 immunohistochemistry significantly increased after PST in human breast cancer tissue." (PMID 21559013, 2011). "At present most of what we know about the role of CSC in breast cancer metastasis has been based on ALDH-positive, CD133-positive or CD44+CD24−/low breast CSC populations." (PMID 24212798, 2011). "Analysis of several breast cancer cell lines revealed the co-expression of Gli-2 and SLUG in only breast cancer cell lines with CD44+/CD24- phenotype." (PMID 20691079, 2010). "There is an overlap with those genes found in a previous report using cells from CD24−/low/CD44+ and CD24+/CD44+ populations derived from normal breast and primary breast cancer tissues." (PMID 19997106, 2010). "In breast cancer cells, the metastatic cell state is strongly correlated to epithelial-to-mesenchymal transition (EMT) and the CD44+/CD24- stem cell phenotype." (PMID 20696077, 2010).
breast cancer (continued). "To determine the hierarchical organisation of breast cancer cell lines, we analysed the tumourigenic potential of the CD24−/low/CD44+ and CD24+/CD44+ cell populations of HCC1954 and MCF7 cell lines." (PMID 19997106, 2010). "The first breakthrough for CSCs in solid tumor systems was in breast cancer, where Al-Hajj analyzed breast cancer stem cells using CD44 and CD24 as markers." (PMID 24281178, 2010). "For breast cancer, CD44+/CD24-/low and aldehyde dehydrogenase (ALDH) have been reported as markers for breast cancer stem cells." (PMID 21044318, 2010). "In breast cancer cell lines, the ALDEFLUOR-population has been divided by the use of CD44+, CD24- and CD133." (PMID 19555472, 2009). "Originally, these tumor-driving cells were identified as a fraction of breast cancer cells with high and low expression of the cell-surface markers CD44 and CD24, respectively." (PMID 19583841, 2009). "The IGS consists of 186 genes which are overexpressed in breast cancer stem cells identified by high expression of CD44 and low expression of CD24 (CD44+CD24-/low), compared to normal breast epithelial cells." (PMID 19664271, 2009). "Breast cancer cell lines were sorted into CD44posCD24pos and CD44posCD24neg populations to evaluate their progeny for the expression of CD44, CD24, and markers of a mesenchymal phenotype." (PMID 19906290, 2009). "In an effort to understand the dynamics of CD24 expression in breast cancer cell lines, cells were sorted based on their CD44 CD24 expression and the CD44/CD24 expression of their progeny was evaluated." (PMID 19906290, 2009). "Here, we showed that CD24 cross-linking is sufficient to inhibit tumor growth, and migration in MCF-7 breast cancer cells." (PMID 18433506, 2008). "Using in vitro-separated tumorigenic cells from malignant human breast cancer-derived pleural effusions, Al Hajj and colleagues isolated a cell population characterized by high CD44 expression and low or undetectable levels of CD24 (CD44+CD24−/low)." (PMID 18682804, 2008). "Subsequent enrichment in Sca-1 positive cancer stem cells was shown for mouse mammary tumor models, such as mouse mammary tumor virus (MMTV)-Her2/neu and MMTV-Wnt1, and Thy1/CD24 expression further defined cancer stem cells in the Wnt1 model." (PMID 18241344, 2008). "In human breast cancers, these tumorigenic breast cancer stem cells are enriched in cells with a CD44+/CD24-/low/ESA+ phenotype." (PMID 18366788, 2008). "Similar to primary breast cancers, cell line derived tumor-initiating cells are enriched in cells with the CD44+/CD24-/low/epithelial-specific antigen (ESA)+ phenotype." (PMID 18366788, 2008). "On the other hand, normal stem cells have been isolated using CD24, CD29, and CD49f in mouse mammary glands, so a single, definitive breast cancer stem cell marker has yet to be defined." (PMID 18433506, 2008). "Our results showed that CD24 cross-linking induced apoptosis and inhibited migration in MCF-7 breast cancer cells." (PMID 18433506, 2008). "In conclusion, we demonstrated that CD24 cross-linking induced apoptosis and inhibited migration ability in MCF-7 human breast cancer cells." (PMID 18433506, 2008). "In contrast, in basal cell lines with high percentages of CD44+/CD24- cells (MDA.MB.231, SUM159, and SUM1315), sorting for ESA+ cells is sufficient to enrich for breast cancer-initiating cells." (PMID 18366788, 2008). "Thus, the unfavourable significance of CD24 expression in breast cancer cells may be explained not only by augmented transfer through the vascular walls but also by the higher proliferative potential of the cells and their increased ability to invade intercellular matrix." (PMID 16892043, 2006). "Five among 13 breast cancer cell lines examined (MDA-MB-231, MDA-MB-436, Hs578T, SUM1315, and HBL-100) contained a higher percentage (>30%) of CD44+/CD24- cells." (PMID 17062128, 2006).
breast cancer (continued). "Using POU1F1-overexpressing and knock-down breast cancer cell lines, as well as immunodeficient mouse models, our data demonstrate that POU1F1 induces a BCSC-like phenotype in breast tumor cells by deregulating markers such as CD24, CD44, CD133, and ALDH." (PMID 41857068, 2026). "A multiplex immunohistochemistry (mIHC) was performed on tumor specimens from ER+ breast cancer patients and based on the expression levels of C4-specific markers (MUCL1 and CD24); these cases were stratified into C4-high invasive and C4-low invasive subgroups." (PMID 41142825, 2025). "Moreover, in recipient breast cancer cells, a significant reduction in cell growth, EMT status, and the cancer stem cell‐enriched CD44+CD24‐ population as observed post‐delivery." (PMID 40059964, 2025). "Cells that are CD44 positive and CD24 negative or low are generally considered to have stem cell-like properties in breast cancer." (PMID 39955575, 2025). "HER2 and CD24 were chosen as complementary, rather than mutually exclusive biomarkers for breast cancer EVs." (PMID 40405296, 2025). "This study demonstrated that pretreatment levels of the CD24, miR590-3p, and miR399-3p differed significantly between patients with pCR to therapy and nonresponders in breast carcinoma." (PMID 40587726, 2025). "Furthermore, ASCs can spontaneously fuse with breast cancer cells, resulting in a population enriched with breast cancer stem cell (CSC) markers such as CD44+CD24−/lowEpCAM+." (PMID 39123496, 2024). "Additionally, in MCF−7 cells, it has been reported that the inhibition of MTH1 increases the proportion of CD44+ CD24−/Low cell subpopulations, suggesting that MTH1 inhibition enhances the number of breast cancer stem cells." (PMID 38543077, 2024). "Surprisingly, we found CD24+ circulating cells (CCs) in peripheral blood of breast cancer patients which have no epithelial markers (EpCAM and cytokeratin 7/8) but was strongly associated with distant metastasis." (PMID 38806508, 2024). "Therefore, in breast cancer patients, the TNM stage, lymph node metastasis, and tumor size are all closely connected to the positive expression of CD24 in CTC." (PMID 38279998, 2024). "There were no discernible differences in the expression of the three prominent breast cancer CSC markers, CD24 (P = 0.066; expression ratio: 0.973), CD133 (P = 0.670; expression ratio:1.02), and CD49f (P = 0.431; expression ratio: 0.907) between the ROR1-high and -low groups." (PMID 38296962, 2024). "Moreover, CD24’s positive impact on the activation of ERK1/2 and Akt (another downstream effector of EGFR) has been observed in CRC and HER2-positive breast cancer cells." (PMID 38881902, 2024). "Astonishingly, Pin1 expression is elevated approximately 6-fold higher in CD24−/CD44+ breast cancer cells (CSCs) relative to non-CD24−/CD44+ breast cancer cells (non-stem cancer cells)." (PMID 38745861, 2024). "In breast cancer stem cells, CD24 expression is downregulated by Twist, an EMT molecule, and it is therefore speculated that CD24 downregulation could be an EMT regulator." (PMID 36979874, 2023). "This ability to dedifferentiate or non-CSC-to-CSC plasticity (for breast cancer CD44-CD24+/- →CD44+CD24-) is determined by ectopic expression of stemness genes, without which such transition is not possible." (PMID 37345102, 2023). "Furthermore, two distinctive stem cell populations were identified in primary human breast cancer cells: CD44-, CD24+, ER+, TGFB-RII- or CD44+, CD24-, ER-, TGFB-RII+ with the latter only being able to undergo EMT due to TGF-β treatment." (PMID 36831452, 2023). "A second trial is underway to evaluate prognostic value of stem cell related markers (CD24, CD44, CD326 and EPCR) for predicting breast cancer recurrence in tumor stages 0-II, but it was withdrawn for lacking of financial support (ClinicalTrials.gov Identifier: NCT01265225)." (PMID 37919766, 2023).
breast cancer (continued). "For example, CD44+CD24−/low and ALDH+ CSCs were characterised in breast cancer, along with CD133+CD44+ in colon, brain, and lung cancer; CD34+CD8− in leukaemia; CD44+ in head and neck tumours; CD90+ in liver cancer; and CD44+/CD24+/ESA+ in pancreatic cancer." (PMID 36902427, 2023). "In addition, CD24 can also influence hedgehog signaling by inhibiting STAT1, resulting in the downregulation of SHH (sonic hedgehog) transcription in breast cancer cells." (PMID 37919766, 2023). "The low expression of CD24 and high expression of aldehyde dehydrogenase 1 family member A1 (ALDH1A1) may define subsets of breast cancer stem cells with enhanced migratory potential." (PMID 37794509, 2023). "However, in breast cancer, the CD44+/CD24− cell population, also known as “breast CSCs,” exhibits considerably greater tumorigenic capability than the CD44+/CD24+ cell population." (PMID 38137380, 2023). "Within the undamaged lipid rafts of breast cancer cells, CD24 interacts with c-Src, enhancing its activity as opposed to modifying the expression level of c-Src." (PMID 38137380, 2023). "We found that, when these breast cancer cell lines lost their attachment to the extracellular matrix, they accumulated a subtype of cancer stem cells (CSC) that expressed the surface markers of stem cells (e.g., CD44+CD24−)." (PMID 36979915, 2023). "Our results showed that knockout of NONO in breast cancer cells significantly reduced the number of CD24−/CD44+ expressing cells." (PMID 37370134, 2023). "Furthermore, after undergoing standard chemotherapy treatment with docetaxel, doxorubicin, cyclophosphamide and trastuzumab, breast cancer cells that are CD44+ and CD24- were found to exhibit resistance to chemotherapy." (PMID 37886168, 2023). "Importantly, this CD24+CD29low feature is a typical characteristic of primary and regenerated MMTV-PyMT mammary tumor cells." (PMID 34976209, 2022). "Third, four hub genes that could have important key functions in tumor growth in breast cancer, MMP1, SDC1, CD24, and SPP1, were identified using GEO and TCGA public datasets as potential prognostic biomarkers." (PMID 35037689, 2022). "Additionally, a decrease in the BCSCs’ CD44+CD24− and ALDH1+ populations was observed, with minimal adverse reactions registered in breast cancer patients." (PMID 35326385, 2022). "Transcriptional regulation of CD24 independent of the DNA methylation status has been described in breast cancers." (PMID 34293822, 2022). "For instance, high expression of CD44 and low expression of CD24 (CD44+/CD24−/low) together with expression of ALDH1 is a feature of breast cancer stem cells as compared to non-stem breast cancer cells." (PMID 35456011, 2022). "snoRNA chips (Oebiotech, Shanghai, China) included 248 snoRNAs that were employed to investigate the differential snoRNAs expression between BCCs (breast cancer cells) and BCSCs, which revealed that SNORA38 was significantly overexpressed in CD44+CD24− subgroup." (PMID 36158687, 2022). "The expression of key markers associated with proliferation (MKI67, PCNA, CCNB1, MYBL2, BUB1, CCND1), apoptosis (BCL2, CASP7, CASP8, CASP9, CASP3, BAX, APAF1), differentiation (CDH1, CD24, EPCAM, ESR1, NGFR, RUNX1), and breast cancer stemness (CD44, ITGA6, DNER, ALDH1A3, ABCG2, PROCR) was assessed." (PMID 35183258, 2022). "We accessed GSE7513 and GSE52327, which consist of gene array data from breast cancer patient tumor cells sorted for CD44+/CD24- or ALDH+ from cells lacking these marker profiles." (PMID 35127497, 2021). "Double immunohistochemistry of human breast cancer tissues showed that p97 expression was significantly higher (p = 3.827 × 10−6) in CD44+/CD24− cells than in the non-CD44+/CD24− cells (i.e., CD44−/CD24−, CD44−/CD24+, and CD44+/CD24+ cells)." (PMID 33731668, 2021). "To test this hypothesis, we first analyzed some of the most commonly accepted markers for breast cancer stem cells, including CD44 and CD24 expression and ALDH activity." (PMID 34315857, 2021).